ALDH6A1 (aldehyde dehydrogenase 6 family member A1)
Description:
Malonate and methylmalonate semialdehyde dehydrogenase involved in the catabolism of valine, thymine, and compounds catabolized by way of beta-alanine, including uracil and cytidine.
Synonyms: MMSDH; MMSADHA
Tractability: Small molecule: it belongs to a druggable protein family. PROTAC: ubiquitination databases record sites on it; its protein half-life has been measured.
Gene: Protein-coding gene on chromosome 14 (74,056,847 to 74,084,492, reverse strand). Ensembl gene ENSG00000119711.
Subcellular location: Mitochondrion
Subcellular location (Human Protein Atlas): Mitochondria
Pathways (Reactome):
Metabolism: Branched-chain amino acid catabolism
Gene Ontology:
Molecular function: methylmalonate-semialdehyde dehydrogenase (acylating, NAD) activity; RNA binding; oxidoreductase activity
Biological process: L-valine catabolic process; thymine catabolic process; branched-chain amino acid catabolic process
Cellular component: mitochondrion; mitochondrial matrix
Genetic constraint (gnomAD): Loss-of-function variants: 41 observed, 63.69 expected, observed/expected ratio (o/e) 0.64, 90% interval 0.5 to 0.83. The synonymous counts are far from expectation, so gnomAD's model fits this gene poorly and the ratio says little. Missense variants: 549 observed, 694.97 expected, observed/expected ratio (o/e) 0.79, 90% interval 0.74 to 0.85. Synonymous variants: 194 observed, 247.53 expected, observed/expected ratio (o/e) 0.78, 90% interval 0.7 to 0.88.
Gene-disease validity (ClinGen):
ClinGen rates the evidence that ALDH6A1 causes each of these diseases.
methylmalonate semialdehyde dehydrogenase deficiency (autosomal recessive): Limited.
Homologues: Orthologues: chimpanzee ALDH6A1 (99% identical), macaque ALDH6A1 (98% identical), dog ALDH6A1 (96% identical), pig ALDH6A1 (96% identical), mouse Aldh6a1 (95% identical), guinea pig ALDH6A1 (94% identical), rat Aldh6a1 (93% identical), rabbit ALDH6A1 (90% identical), zebrafish aldh6a1 (81% identical), tropical clawed frog aldh6a1 (78% identical), Drosophila melanogaster CG17896 (65% identical), Caenorhabditis elegans alh-8 (64% identical). Paralogues in human: ALDH1A3 (30% identical), ALDH1A1 (29% identical), ALDH1A2 (29% identical), ALDH1B1 (29% identical), ALDH2 (28% identical), ALDH1L2 (27% identical), ALDH9A1 (27% identical), ALDH1L1 (27% identical), ALDH8A1 (26% identical), ALDH5A1 (25% identical), ALDH7A1 (22% identical), ALDH4A1 (20% identical), and 5 more.
Diseases named in the same sentence as ALDH6A1 in open-access papers:
ALDH6A1 is named in the same sentence as 50 diseases in open-access papers, as found by Europe PMC text mining. Sharing a sentence is not in itself a finding about the gene and the disease. The quoted sentences say what the papers report.
breast carcinoma (7 papers, 2015 to 2025). "We identified nine cancer cell subclusters including CD44 + / ALDH2 + /ALDH6A1 + breast cancer stem cells (BCSCs), which had a copy-number variants profile similar to that of normal breast tissue." (PMID 34611125, 2021). "EPCAM and KRT18 were employed to label epithelial cells, whereas ALDH2, CD55, and ALDH6A1 were used to identify breast cancer stem cells." (PMID 40092692, 2025). "Studies have also shown that ALDH6A1 was positively expressed in breast cancer stem cells, and gradually decreased during tumor progression." (PMID 35873461, 2022). "In the present study, we isolated the CD44 + /ALDH2 + /ALDH6A1 + breast cancer stem cells (BCSCs) and proved the pluripotency according to trajectory analysis and RNA-velocity." (PMID 34611125, 2021). "A CD44 + / ALDH2 + /ALDH6A1 + cluster was defined as breast cancer stem cells (BCSCs)." (PMID 34611125, 2021).
hepatocellular carcinoma (7 papers, 2020 to 2025). A malignant tumor that arises from hepatocytes. "A study on ALDH6A1 as a potential biomarker of hepatocellular carcinoma showed that an increase in ALDH6A1 in ALDH6A1-O/E cells would cause a reduction in NAD+/NADH, which consequently disrupts mitochondrial membrane potential." (PMID 40467924, 2025). "Recent research supported decreases in Pro-CoA and its derivative propionyl-l-carnitine due to ALDH6A1 downregulation were tightly associated with hepatocellular carcinoma." (PMID 38551775, 2024). "ABAT and ALDH6A1 are proved to be hub genes in association with metastasis risk and prognosis in hepatocellular carcinoma (HCC)." (PMID 32093682, 2020). "It was shown that the expression of Aldh6a1 is reduced ten times in different hepatocellular carcinomas, while hepatic carcinoma mitochondria are extremely resistant to calcium." (PMID 37830628, 2023). "ALDH6A1 is reported to be regulated in several processes of cancer, including hepatocellular carcinoma and prostate cancer, and diabetes." (PMID 37395176, 2023). "The decrease of reactive oxygen species (ROS) and the elevation of nitric oxide (NO) in hepatocellular carcinoma were probably related to the low expression of ALDH6A1." (PMID 36098688, 2022). "Meanwhile, ALDH6A1 was identified as a potential molecular signature for hepatocellular carcinoma, prostate cancer, and muscle insulin resistance in type 2 diabetes mellitus." (PMID 36176391, 2022). "Additionally, through comprehensive evaluation of quantitative proteomic profiling and molecular features, a study found that ALDH6A1 expression decreased in hepatocellular carcinoma cells." (PMID 36098688, 2022).
metastatic prostate carcinoma (5 papers, 2019 to 2022). A carcinoma that arises from the prostate gland and has spread to other anatomic sites. "Meanwhile, another study has shown that hypo-expression of ALDH6A1 was associated with survival of metastatic prostate cancer patients." (PMID 36098688, 2022). "Meanwhile, two-dimensional gel electrophoresis and mass spectrometry analyses indicated that ALDH6A1 was highly specific to metastatic tumor cells and its expression was significantly reduced in metastatic prostate cancer." (PMID 33686951, 2021). "Recently, proteomic analysis of primary and metastatic prostate cancer has also demonstrated that ALDH6A1 is highly specific to progressive metastatic disease." (PMID 31941033, 2020).
atherosclerosis (3 papers, 2016 to 2023). A disease characterized by the build-up of fatty material and calcium deposition in the arterial wall resulting in partial or complete occlusion of the arterial lumen. "ALDH6A1 is a member of the ALDH superfamily, which is highly involved in ROS production which increases dramatically in atherosclerosis." (PMID 36685865, 2022).
clear cell renal cell carcinoma (3 papers, 2020 to 2023). "The downregulated ALDH6A1 has been proved to regulate the immune response in clear cell renal cell carcinoma, which implied a new biomarker for the clinical immunotherapy of ccRCC patients." (PMID 36098688, 2022). "Specifically, ALDH6A1 is regulated by a well‐known suppressor transcription factor HNF4A, which suppressed tumorigenic capability in clear renal cell carcinoma." (PMID 37395176, 2023). "ALDH6A1, as a potential target gene of HNF4A, could suppress the proliferation and metastasis of clear renal cell carcinoma (ccRCC)." (PMID 36098688, 2022).
colon cancer (3 papers, 2014 to 2023). "To conclude, we identified two distinct qPCR gene expression profiles correlating with response (low expression of ALDH6A1 + TFF2 + MCM5) and with PFS (KLF12-high + TFF2-low) in advanced colon cancer patients managed with bevacizumab and chemotherapy." (PMID 24555920, 2014).
developmental delay (3 papers, 2013 to 2022). "And ALDH6A1 is found in the liver, kidneys, heart, brain, and muscle and its deficiency results in developmental delay, which might play a role in the process of AS." (PMID 36685865, 2022).
diabetes (3 papers, 2022 to 2023). "In addition, tyrosine nitration of Aldh6a1 is enhanced in rat kidney mitochondria upon the development of diabetes mellitus Type 1 and acute septic damage and in heart mitochondria in aging." (PMID 37830628, 2023).
Methylmalonic aciduria (3 papers, 2015 to 2025). Increased concentration of methylmalonic acid in the urine. "Mutations of ALDH6A1 are associated with methylmalonic aciduria in humans." (PMID 41306553, 2025).
renal cell carcinoma (3 papers, 2019 to 2020). "Based on the pan-cancer analysis, both ABAT and ALDH6A1 were significantly down-expressed in three types of renal cell carcinomas, KIRC, kidney renal papillary cell carcinoma (KIRP), and kidney chromophobe (KICH)." (PMID 32093682, 2020).
bladder cancer (2 papers, 2023). "Low expression of ALDH6A1 is positively associated with advanced cancer subtype and cisplatin resistance, hinting at a poorer outcome in bladder cancer patients." (PMID 36694633, 2023). "An in vitro and in vivo study has shown that the knockdown of ALDH6A1 can promote cancer growth and reduce response to chemotherapy cisplatin through the negative regulation of the hepatocyte nuclear factor 4 alpha (HNF4α) in bladder cancer." (PMID 37476181, 2023). "ALDH6A1 is remarkably downregulated in bladder cancer tissues and cell lines." (PMID 36694633, 2023).
cognitive decline (2 papers, 2023 to 2025). "For example, ALDH6A1 differentially expressed for global AD pathology in the discovery data was replicated with P-value = 0.008 for cognitive decline in SMA and muscle." (PMID 37789141, 2023).
ovarian carcinoma (2 papers, 2023 to 2024). A malignant neoplasm originating from the surface ovarian epithelium. "Aldehyde dehydrogenases (ALDH4A1 and ALDH6A1) overexpression has been shown to be associated with poorer overall patient survival, particularly in breast, head and neck, cervical and ovarian cancers." (PMID 39403185, 2024).
amyloidosis (1 paper, 2020). A disorder characterized by the localized or diffuse accumulation of amyloid protein in various anatomic sites. "We also profiled CSF in the 5xFAD mouse model to validate amyloidosis-induced changes, and found consistent mitochondrial decreases (SOD2, PRDX3, ALDH6A1, ETFB, HADHA, and CYB5R3) in both human and mouse samples." (PMID 32711556, 2020).
atrial fibrillation (1 paper, 2025). A disorder characterized by an electrocardiographic finding of a supraventricular arrhythmia characterized by the replacement of consistent P waves by rapid oscillations or fibrillatory waves that vary in size, shape and timing and are accompanied by an irregular ventricular response. "The alterations of lysine propionylation modifications in the human right atrium reveal the important mechanism of ALDH6A1-NADH pathway in the pathogenesis of new-onset atrial fibrillation following coronary artery bypass grafting." (PMID 40467924, 2025).
cardiac hypertrophy (1 paper, 2020). "Fatty acid oxidation (Acadm, Etfdh, Acadl, Acadvl, Eci1, Hadh, Phyh, Acaa2, Hadha, Hadhb, Cd36), glucose metabolism (Dld, Pdha1, Pgam1, Pgam2, Acss1, Ldhb, Fh1, Slc2a4, Aldh6a1), TCA cycle (Aco2, Dld, Fh1, Ogdh, Sucla2, Sdha, Idh3b, Idh2) were up-regulated by hispidulin in cardiac hypertrophy." (PMID 33324687, 2020).
gastric cancer (1 paper, 2022). A primary or metastatic malignant neoplasm involving the stomach. "Two GSE datasets indicated that the level of ALDH6A1 expression was downregulated in gastric cancer (p < 0.0001)." (PMID 36098688, 2022). "Our study is for the first time to figure out the drug-metabolism related gene ALDH6A1 expression was low in gastric cancer group." (PMID 36098688, 2022). "In addition, we evaluated the correlation between ALDH6A1 expression and immune regulation of gastric cancer through the statistics obtained from the TCGA database." (PMID 36098688, 2022). "Bioinformatics platforms that are used to evaluate the significance of ALDH6A1 in gastric cancer." (PMID 36098688, 2022). "Whereas, there is no study that focuses on the relationship between gastric cancer patients and the expression level of ALDH6A1." (PMID 36098688, 2022).
glioma (1 paper, 2021). A benign or malignant brain and spinal cord tumor that arises from glial cells (astrocytes, oligodendrocytes, ependymal cells). "In the LGG cohort from the TCGA dataset, ALDHs including ALDH2, ALDH6A1, ALDH5A1, ALDH9A1, ALDH1A1 were upregulated in WHO grade II gliomas while the increased expression of ALDH16A1, ALDH3B1, ALDH3A2, ALDH1A2, ALDH3A1 was found in WHO III grade gliomas." (PMID 35116021, 2021). "Analysis of the TCGA dataset showed that ALDH16A1, ALDH3B1, ALDH1A3, ALDH3A1, ALDH7A1 were significantly increased in IDH wildtype gliomas, while ALDH2, ALDH6A1, ALDH5A1, ALDH1A1, ALDH1L2, ALDH18A1, ALDH1B1 expression were higher in IDH mutant gliomas than IDH wildtype gliomas." (PMID 35116021, 2021).
kidney cancer (1 paper, 2021). Primary or metastatic malignant neoplasm involving the kidney. "The information available indicated that ALDH6A1 expression in kidney cancer is significantly lower than in normal kidney tissue." (PMID 33686951, 2021).
liver cancer (1 paper, 2023). An epithelial or non-epithelial malignant neoplasm that arises from the liver. "Another study showed that inhibition of ALDH6A1 may be strongly associated with abnormal proliferation of liver cancer cells." (PMID 37395176, 2023).
methylmalonic acidemia (1 paper, 2023). A genetically heterogenous inherited disorder characterized by abnormalities in the metabolism of lipids and proteins. "Mutations in the ALDH6A1 cause methylmalonic acidemia, which is a devastating metabolic disorder with a poor prognosis." (PMID 36694633, 2023).
MMSDH deficiency (1 paper, 2013). "Whole exome sequencing identified two novel variants in the gene ALDH6A1, supporting a diagnosis of MMSDH deficiency." (PMID 23835272, 2013).
Obesity (1 paper, 2022). Accumulation of substantial excess body fat. "Abcg1, Aldoa, Mrap, Pex13, Aldh6a1, Egln3, G0s2 and Syn2 are significantly increased in adipose or liver tissue of ob/ob mice compared with lean mice, suggesting these genes are associated with obesity, are very rarely reported to be related to adipogenesis." (PMID 34974794, 2022).
renal carcinoma (1 paper, 2020). A carcinoma arising from the epithelium of the renal parenchyma or the renal pelvis. "Overexpression of ABAT or ALDH6A1 reduced cell proliferation and migration and impaired oncologic metabolism of renal cancer cells." (PMID 32093682, 2020). "By measuring the lactic acid production and NADP/NADPH ratio of renal cancer cells, the results showed that after ABAT or ALDH6A1 overexpression, oncologic metabolism was impaired." (PMID 32093682, 2020). "In order to understand the mechanism of overexpressing ABAT or ALDH6A1 in renal cancer cells, database analysis shows that ABAT and ALDH6A1 are mainly involved in oncologic metabolism." (PMID 32093682, 2020).
rhabdomyosarcoma (1 paper, 2020). A rare aggressive malignant mesenchymal neoplasm arising from skeletal muscle. "Using our model of gradual selection of rhabdomyosarcoma CSCs, we revealed an apparent upregulation of ALDH6A1 at mRNA and protein level, which was associated with Aldefluor positivity and increased stemness, while ALDH1A1 gene expression was markedly downregulated." (PMID 31941033, 2020). "In contrast, our model utilizing primary tumor-derived cells suggests ALDH6A1 as a candidate molecule that plays a role in rhabdomyosarcoma CSCs." (PMID 31941033, 2020). "Indeed, the expression of ALDH6A1 has already been identified among the genes that correlate with poor outcome in rhabdomyosarcoma patients." (PMID 31941033, 2020). "This approach enabled us to identify several novel and promising rhabdomyosarcoma CSC-specific targets, e.g., ALDH6A1, SOX4, PAX3, CDH15, downregulated MIR145, or phosphorylated RYK, which warrant validation in subsequent mechanistic studies." (PMID 31941033, 2020).
soft tissue sarcoma (1 paper, 2020). A malignant neoplasm arising from muscle tissue, adipose tissue, blood vessels, fibrous tissue, or other supportive tissues excluding the bones. "This is in agreement with our survival analysis on soft-tissue sarcomas demonstrating that upregulated expression of ALDH6A1 but not ALDH1A1 or ALDH3A1 significantly correlates with poor survival when combined with other genes identified in our model, i.e., CDH15, MYOD1, SOX4, ARMCX1, and RYK." (PMID 31941033, 2020).
tumor (16 papers, 2014 to 2025). "A marked positive granular signal for ALDH6A1 was evident in the cytoplasm of almost all tumor cells, probably associated with mitochondria, while a more diffuse cytosolic positivity was detected for Transferrin and Fascin-1 in ACC slices." (PMID 25691058, 2015). "Our study identified that loss of ABAT and ALDH6A1 contributes to ccRCC tumor growth." (PMID 32093682, 2020). "Finally, the profile of all-low (ALDH6A1 + TFF2) tumor gene expression showed a marginally significant association with superior survival in the chemotherapy-only Control set, but not in the Bevacizumab qPCR set." (PMID 24555920, 2014). "In ccRCC, NFIC and GATA2 regulate ALDH6A1 expression, enhancing its capacity to manage oxidative stress and detoxify harmful metabolites, which is crucial in the tumor environment." (PMID 39348357, 2024). "Residues at positively selected sites of CDR2L and ALDH6A1 in these long‐lived mammals enhanced the inhibition of tumor cell migration compared to those in short‐lived relatives." (PMID 37395176, 2023). "Residues of CDR2L and ALDH6A1 in long‐lived mammals enhanced the inhibition of tumor cell migration." (PMID 37395176, 2023). "Overexpression of ALDH6A1 reduces cell growth and migration and impairs tumor metabolism of ccRCC cells." (PMID 36694633, 2023). "A previous study indicated that ABAT and aldehyde dehydrogenase 6 family member A1 (ALDH6A1) worked as a tumor suppressor in ccRCC, thereby suppressing tumorigenic capability." (PMID 36176391, 2022). "We also demonstrated that ABAT and ALDH6A1 are directly regulated by a well-known tumor suppressor, transcription factor HNF4A." (PMID 32093682, 2020). "The results still showed decreased expression of ABAT and ALDH6A1 in tumor compared with paraneoplastic tissues (p < 0.0001)." (PMID 32093682, 2020). "By controlling the metabolism of aldehydes, the key gene ALDH6A1 might have an impact on detoxification procedures, intermediate metabolism, and cellular redox balance, all of which might accelerate the tumor’s development in kidney." (PMID 39348357, 2024). "ALDH6A1 could be a key player in immune modulation within the tumor microenvironment." (PMID 39348357, 2024). "We established A549 cells with ALDH6A1 or ALDH9A1 depletion and found that ALDH9A1 depletion increased tumor cell death in confining pores, though its effect was weaker than that of ALDH1B1 ablation." (PMID 41390768, 2025). "We also observed differences in ALDH2 levels between tumor and normal tissues based on HPV status, anatomic subsite, and potential interactions between ALDH2 and ALDH6A1." (PMID 37476181, 2023). "The expression of ALDH6A1 and ETFDH was downregulated in tumor samples, and the remaining ten genes were upregulated in tumor samples as compared with normal samples." (PMID 36105252, 2022). "Meanwhile, RT-qPCR assays revealed that ALDH6A1, FBP1, HAO2 and PSAT1 were markedly under-expressed in tumor tissues in exceeding 60% cases, and that TYMP, HK3, P4HA3, IL4I1, CYP26A1 and CPT1B were over-expressed in tumor tissues in exceeding 70% cases." (PMID 32737333, 2020). "Tumor tissue samples from patients with unfavorable PFS status were found to overexpress four out of the five genes (AGR2, ALDH6A1, TFF2, MCM5) and underexpress KLF12." (PMID 24555920, 2014). "The expression levels of ACADL, ACADS, ACADSB, ALDH6A1, ETFDH, and GCDH were found to be lower in tumor samples compared to normal samples, whereas the expression levels of CCNB1 and CDK1 were observed to be higher in tumor than in normal samples." (PMID 37994323, 2023). "Some adhesion molecules play an important role in tumor recurrence, metastasis, and invasion.(Okegawa, Pong, Li, & Hsieh, 2004) Based on the construction of PPI network and module analysis, ACAA1, ACADSB, ALDH6A1, AUH, HADH,and PCCA with high degree of connectivity were selected as hub genes." (PMID 30793530, 2019).